USP37 (ubiquitin specific peptidase 37)
Diseases named in the same sentence as USP37 in open-access papers (continued):
Sharing a sentence is not in itself a finding about the gene and the disease.
breast carcinoma (continued). "Therefore, targeting USP37 in the breast cancer may sensitize cancer to cisplatin or IR treatment." (PMID 34606619, 2021). "We tested the expression profile of USP37 and BLM in normal breast epithelium and a number of breast cancer cell lines, and found that both of them were over-expressed in the breast cancer cell lines." (PMID 34606619, 2021). "Next, we detected the expression of USP37 and BLM in human breast cancer samples by immunohistochemical (IHC) analyses." (PMID 34606619, 2021). "Recently, our group has found that the expression level of USP37 is exceptionally upregulated in CD44+/CD24- phenotype breast cancer stem cells, and can regulate the stemness of breast cancer cell through its interaction with GLI-19." (PMID 33390801, 2021). "Knockdown of USP37 impairs the DDR through BLM and results in increased sensitivity to cisplatin or IR treatment in breast cancer cells." (PMID 34606619, 2021). "Finally, considering that USP37 is overexpressed in breast cancer, small molecules that inhibit USP37 have broad development prospects and a combination of USP37 inhibitor with platinum-based therapy or IR may provide a novel approach for breast cancer therapy." (PMID 34606619, 2021). "Preliminary studies of our team have established that USP37 regulates the stemness, cell invasion, and EMT in breast cancer cells." (PMID 33390801, 2021). "Knockdown of USP37 suppressed mammospheres formation and inhibited cancer stem markers, such as ALDH1and OCT4 in breast cancer cells." (PMID 30482232, 2018). "USP37 regulated the ability of cell invasion, epithelial-mesenchymal transition (EMT), stemness and cisplatin sensitivity in breast cancer cell lines." (PMID 30482232, 2018). "However, the biological functions of USP37 in breast cancer remain unclear." (PMID 30482232, 2018). "USP37 can regulate the stemness, cell invasion and EMT via Hh pathway, and decreased USP37 confers sensitivity to cisplatin in breast cancer cells." (PMID 30482232, 2018). "Based on this experimental data, we were able to further demonstrate that USP37 is involved in regulating EMT in breast cancer progression and promotes the migration and invasion capacity of breast cancer cells." (PMID 30482232, 2018). "Our findings indicate that the USP37–BLM axis plays a critical role in the cellular response to cisplatin or IR treatment in breast cancer, supporting the pursuit of molecules targeting this pathway in breast cancer intervention." (PMID 34606619, 2021). "For example, USP37 can interact with Hedgehog pathway components Smo and Gli-1 to stabilize these proteins and is essential for stemness maintenance, cell invasion, and EMT in breast cancer." (PMID 31998374, 2019). "Further studies indicated that USP37 knockdown could inhibit the stemness, cell invasion and EMT in breast cancer via downregulation of Hh pathway." (PMID 30482232, 2018). "In summary, our data showed that USP37 could regulate the migration, invasion, EMT of breast cancer cells." (PMID 30482232, 2018). "To further confirm the overexpression of USP37 gene in breast cancer, we utilized a series of human breast cancer cells (MCF-7, MDA-MB-231, BT549 and T47D) and human normal breast epithelial cells (MCF-10A) to examine USP37 protein expression by western blotting." (PMID 30482232, 2018). "The Hh pathway is considered to control the self-renewal of CSCs in breast cancer; therefore, we tested the expression of representative Hh signaling factors (smoothened and Gli-1) and main stem cell markers (ALDH1 and OCT4) in USP37 knockdown cells and control cells by western blotting analysis." (PMID 30482232, 2018). "However, it is not explicit whether the knockdown of USP37 gene expression can re-sensitize the adriamycin-resistant breast cancer cells." (PMID 33390801, 2021).
lung carcinoma (14 papers, 2018 to 2026). "Immunohistochemical analysis revealed that USP37 is upregulated in 64% of human lung cancer tissues and is associated with c-MYC expression." (PMID 34758854, 2021). "More importantly, high expression level of USP37 is associated with poor survival and prognosis of lung cancer patients, where the high expression level of Snail is also associated with poor survival and prognosis." (PMID 31998374, 2019). "Because USP37 is highly expressed in patients with LC, OSAH and LC cell lines, USP37 may be involved in OSAH-associated lung cancer progression." (PMID 34758854, 2021). "Another study in lung cancer suggested that USP37 has been shown to directly deubiquitinate MYC and block its degradation, and MYC expression has been associated with poor patient prognosis in osteosarcoma." (PMID 37118828, 2023). "USP37 stabilizes MYC in lung cancer and the oncogenic fusion protein PLZF/RARA in Acute promyelocytic leukaemia (APL)." (PMID 37118828, 2023). "USP37 has been found to regulate the turnover of c-MYC in lung carcinoma by direct physical interaction." (PMID 36985413, 2023). "At the transcriptional level, two tumor suppressor miRNAs in HCC and lung cancer with OSAH are involved in regulating USP37 transcription." (PMID 34758854, 2021). "In a study about the pathogenesis of lung cancer, highly-expressed USP37 was proven to promote cell proliferation, enhance the Warburg effect, and increase the mortality rate and metastasis." (PMID 33390801, 2021). "The results are consistent with the previous reports that USP37 knockdown significantly inhibited the tumor formation of malignancies, such as lung cancer 18, kidney cancer 19, hepatocellular cancer." (PMID 33390801, 2021). "Other work shows that USP37 stabilizes c-Myc in lung cancer, promoting lung cancer cell proliferation." (PMID 34606619, 2021). "Our data showed that USP37 directly binds and deubiquitinates Snail and can markedly prevent Snail degradation; biologically, USP37 promotes lung cancer cell migration, and Snail is an essential substrate for USP37-mediated cell migration." (PMID 31998374, 2019). "Recent data have reported that the expression of USP37 is elevated in various types of cancers, including breast and lung cancers, and is strongly correlated with the increased mortality rate and metastasis." (PMID 31998374, 2019). "To examine the role of USP37 in cell migration, we expressed USP37 WT and USP37-C350S mutant in lung cancer H1299 cells, and the transfected cells were prepared for Western blotting and cell migration assays." (PMID 31998374, 2019). "Our studies showed that ectopically expressed Flag-USP37 was able to immunoprecipitate endogenous Snail protein in lung cancer H1299 cells." (PMID 31998374, 2019). "In lung cancer cells, USP37 promotes cell proliferation and enhances the Warburg effect by directly interacting with c-Myc to deubiquitinate c-Myc." (PMID 31998374, 2019). "Biologically, upregulated expression of USP37 promotes lung cancer cell migration, while depletion of Snail abolishes the effect of USP37." (PMID 31998374, 2019). "Additionally, USP37 has been reported to promote the Warburg effect in cancer cells and the proliferation of lung cancer cells by deubiquitinating Myc." (PMID 39146353, 2024). "In different cancers, cellular turnover of c-MYC has been regulated by different USPs, with notable examples including the maintenance of c-MYC turnover by direct physical interactions of USP28 in colon carcinoma, USP36 in breast carcinoma and USP37 in lung cancer." (PMID 36985413, 2023). "In lung cancers, USP37 expression is upregulated and positively correlated with Myc, suggests that USP37-Myc inhibitors may be a therapeutic strategy for lung cancer." (PMID 34658888, 2021). "Furthermore, USP37 deubiquitinates c-MYC in lung cancer H1299 cells and drives proliferation and the Warburg effect." (PMID 34758854, 2021).
lung carcinoma (continued). "Moreover, USP37 induces c-Myc activity by suppressing its degradation, while the inhibition of USP37 increases c-Myc recycling in lung cancer." (PMID 32882786, 2020). "USP37 has been previously confirmed to be overexpressed in lung cancers cells and tissues." (PMID 30482232, 2018). "We speculate that the expressions of USP37 and Snail in lung cancer are positively correlated." (PMID 31998374, 2019). "Bioinformatics analysis demonstrates that these DUBs except USP47 are upregulated and overall survival analysis indicates that lower expression of these DUBs, except USP37 and USP49, is correlated with improved overall survival in lung cancer patients." (PMID 41399373, 2026). "Multiplex RT-PCR showed distinct mRNA expression profiles of several DUB genes, including USP35, USP36, USP37, USP47, USP49, and OTUD6B in A549 lung cancer cells following exposure to cisplatin." (PMID 41399373, 2026). "In colon carcinoma and lung cancer, c-MYC expression is maintained by USP28 and USP37, respectively." (PMID 36985413, 2023). "USP36 and USP37 have been reported to regulate tumorigenesis by preventing MYC degradation in breast and lung cancer [16,35,]." (PMID 34272356, 2021). "Following the observation of altered expression levels of USP35, USP36, USP37, USP47, USP49, and OTUD6B in response to cisplatin treatment in lung cancer cells, both at the mRNA and protein levels, we sought to explore their significance in lung cancer." (PMID 41399373, 2026). "It consists of three members, USP26, USP29 and USP37, of which USP26 is a positive regulator of Androgen Receptor in prostate cancer cells, USP37 directly deubiquitinates and stabilizes c-Myc in lung cancer, and USP29 has been recognized as a regulator of the checkpoint adaptor Claspin." (PMID 34272356, 2021). "Therefore, USP37 is a potent oncogene that drives the expression of the c-MYC oncoprotein and lung cancer oncogenesis." (PMID 34758854, 2021). "Furthermore, expression of wild-type but not a catalytically dead mutant of USP37 induces a migratory phenotype in lung cancer cells." (PMID 34758854, 2021). "Substantiating these findings, western blotting analysis confirmed the protein expression levels of USP35, USP36, USP37, USP47, USP49, and OTUD6B in cisplatin-treated lung cancer cells, mirroring the mRNA trends observed in non-treated counterparts except for OTUD6B." (PMID 41399373, 2026).
gastric cancer (11 papers, 2021 to 2025). A primary or metastatic malignant neoplasm involving the stomach. "In gastric cancer, USP37 enhances cell proliferation and migration by deubiquitinating and stabilizing Snail1 in a PLAGL2-dependent manner." (PMID 40926837, 2025). "It has been shown that PLAGL2 promoted EMT by USP37-mediated deubiquitination of Snail1 in gastric cancer, as well as β-catenin-dependent regulation of ZEB1 in colorectal cancer." (PMID 34944712, 2021). "Moreover, PLAGL2 had a critical biological role in promoting the malignant phenotypes of gastric cancer cells through USP37-mediated deubiquitination of Snail protein." (PMID 36879254, 2023). "In gastric cancer, overexpression of PLAGL2 facilitates the proliferation and migration of gastric cancer cells and contributes to the process of epithelial–mesenchymal transition (EMT) via the USP37-Snail1 axis." (PMID 35565203, 2022). "A recent report suggested that USP37-mediated deubiquitination of SNAI1 could promote the proliferation and migration of gastric cancer cells." (PMID 36768307, 2023). "USP37 and MACC1 were down-regulated after up-regulation of miR-BART1-3p, which may be the key target genes for miR-BART1-3p to regulate the proliferation of gastric cancer cells through exosomes." (PMID 37345178, 2023).
colon carcinoma (4 papers, 2016 to 2026). "USP32, USP1, USP37, USP12, and USP6 are elevated in macrophages, while USP32, USP9X, USP46, USP12, USP36, and USP24 are upregulated in classical monocytes of colon cancer relative to the control group." (PMID 41356798, 2026). "c-Myc-dependent tumors (adenocarcinomas and non-small lung, breast, and colon cancer) could potentially respond to USP28, USP36, USP37, all DUBs affecting c-Myc protein turnover." (PMID 27516771, 2016).
hepatocellular carcinoma (4 papers, 2014 to 2025). A malignant tumor that arises from hepatocytes. "This study has relied on the cell culture-based system where HBx was co-expressed along with USP37-DD or USP37 either in immortalized human hepatocytes or in hepatoma Huh7 cells to elucidate the oncogenic cooperation between HBx and USP37." (PMID 25347529, 2014). "Additionally, USP37 contributes to chemoresistance in hepatocellular carcinoma (HCC) by maintaining NRF2 protein stability." (PMID 40926837, 2025). "In contrast, positive regulation of USP37 is associated with increased cyclin A/CDK2 activity and development of hepatocellular carcinoma (HCC) by the hepatitis B virus HBx oncoprotein." (PMID 34758854, 2021).
medulloblastoma (4 papers, 2014 to 2021). A malignant, invasive embryonal neoplasm arising from the cerebellum. "In medulloblastoma, G9a drives H3K9me1/2/3 at the promoter of ubiquitin-specific protease 37 (USP37) to repress its gene expression." (PMID 34685453, 2021). "Constitutive expression of USP37 promotes p27 deubiquitination in medulloblastoma cells, whereas a catalytically dead USP37 mutant is unable to stabilize p27." (PMID 34758854, 2021). "USP37 also plays a role in stabilizing tumor suppressor p27 in medulloblastoma cells and promyelocytic leukemia zinc finger and retinoic acid receptor alpha (PLZF-RARA) oncogenic fusion protein in Acute promyelocytic leukemia." (PMID 25347529, 2014). "Overall, USP37 functions as a tumor suppressor in medulloblastoma, but its effects on other oncogenes and transcription factors involved in oncogenesis and cell metastasis remain unclear." (PMID 34758854, 2021). "USP37 is a tumor promoter in many cancers but also acts as a tumor suppressor in medulloblastoma." (PMID 34758854, 2021). "Ambiguously, the transcription of USP37 is suppressed in medulloblastoma cells through the activity of RE1 silencing transcription factor to prevent the USP37-mediated stabilization of the cyclin-dependent kinase inhibitor p27, which is known to act as a negative regulator of cell cycle." (PMID 25347529, 2014). "In medulloblastomas, REST expression could decrease cyclin-dependent kinase (CDK)NIB/p27 (a CDK inhibitor) by repressing ubiquitin specific peptidase 37 (USP37), which could form a complex with p27 to promote its deubiquitination and stabilization, and resulting in blocked cell proliferation." (PMID 27153061, 2016).
acute promyelocytic leukemia (2 papers, 2014 to 2018). An aggressive form of acute myeloid leukemia (AML), characterized by arrest of leukocyte differentiation at the promyelocyte stage, due to a specific chromosomal translocation t(15;17) in myeloid cells. "Subsequently, it was verified that USP37 expression modulated the oncogenic fusion protein PLZF/RARA stability and cell transformation potential in PLZF/RARA-associated acute promyelocytic leukemia." (PMID 30482232, 2018).
colorectal cancer (2 papers, 2021 to 2025). A primary or metastatic malignant neoplasm that affects the colon or rectum. "For example, USP37 facilitates angiogenesis and metastasis in colorectal cancer by stabilizing β-catenin, while its interaction with PCNA drives osteosarcoma pathogenesis by modulating replication fork progression." (PMID 40926837, 2025).
kidney cancer (2 papers, 2021 to 2023). Primary or metastatic malignant neoplasm involving the kidney. "In Clear cell renal cell carcinoma (ccRCC), USP37 binds to and stabilizes HIF2α, promoting kidney cancer tumorigenesis." (PMID 37118828, 2023).
non-small cell lung carcinoma (2 papers, 2014 to 2019). A group of at least three distinct histological types of lung cancer, including non-small cell squamous cell carcinoma, adenocarcinoma, and large cell carcinoma. "For instance, increased USP37 expression is correlated with poor prognosis in non-small cell lung cancer." (PMID 25347529, 2014). "In addition, high level of Snail and USP37 in non-small cell lung carcinoma (NSCLC) patients showed poor survival." (PMID 31998374, 2019).
osteosarcoma (2 papers, 2023 to 2025). A usually aggressive malignant bone-forming mesenchymal neoplasm, predominantly affecting adolescents and young adults. "Analysis of the TCGA database revealed that increased expression of USP37 was linked to decreased progression-free survival (PFS) in osteosarcoma patients." (PMID 37118828, 2023). "We have also found that the expression of USP37 is linked to PCNA in archived osteosarcoma patient samples." (PMID 37118828, 2023). "TCGA data from 262 osteosarcoma patients indicated that USP37 transcript levels were significantly elevated and correlated with reduced OS and DFS in patients." (PMID 37118828, 2023). "The results of this investigation propose that USP37 plays a vital role in promoting replication stress tolerance in osteosarcoma cells." (PMID 37118828, 2023). "We then analyzed the cellular localization of USP37 in response to replication stress by treating osteosarcoma cells with HU and isolating the nuclear and cytoplasmic fractions." (PMID 37118828, 2023). "This study has expanded our knowledge of the mechanism through which USP37 regulates replication stress, and its potential as a therapeutic target in osteosarcoma merits additional exploration." (PMID 37118828, 2023). "Our findings show that in osteosarcoma cells, USP37's interaction with PCNA plays a role in supporting the stability of the replication fork." (PMID 37118828, 2023). "The expression of USP37 varied in archived osteosarcoma tissues, with intermediate expression seen in 52% of cases in the cohort examined." (PMID 37118828, 2023). "To further validate these findings, we transfected U2OS osteosarcoma cells with Myc USP37 plasmid and treated them with 300 μM HU for 24 h." (PMID 37118828, 2023). "The study conducted RNA sequencing analysis in osteosarcoma cells to better understand the transcriptome regulated by USP37 and the possible pathways it regulates." (PMID 37118828, 2023). "Elevated levels of USP37 were found in osteosarcoma cells, and it was discovered that overexpression of USP37 led to enhanced survival in response to replication stress, while its depletion led to reduced survival." (PMID 37118828, 2023). "Upon exposure of the cells to HU-mediated replication stress and subsequent visualization using immunofluorescence, an increase in the level of USP37 protein and a change in its localization pattern were observed in both osteosarcoma cell lines." (PMID 37118828, 2023). "Induction of replication stress led to an increase in USP37 expression in osteosarcoma cells, which correlated with elevated levels of the DNA damage marker, γH2AX." (PMID 37118828, 2023). "After a correlation of OS and DFS was seen with the expression of USP37, we modulated the expression of USP37 by overexpression and depletion of USP37 to identify its molecular targets in osteosarcoma especially pertaining to replication stress." (PMID 37118828, 2023). "The study examined the role of USP37, a protein that regulates DNA replicative stress, in osteosarcoma cells." (PMID 37118828, 2023). "MYC expression, a protein stabilized by USP37, is strongly related to many sarcomas, including osteosarcoma." (PMID 37118828, 2023). "In our study, we found that PCNA levels increase in response to replication stress in osteosarcoma cells, and we discovered that USP37 interacts with PCNA." (PMID 37118828, 2023). "Next-generation sequencing analysis of osteosarcoma cells demonstrated that overexpression or knockdown of USP37 led to the expression of different sets of genes." (PMID 37118828, 2023). "Similar to patient data, increased expression of USP37 was seen in osteosarcoma cell lines U2OS and MG-63 both at both mRNA and protein level as compared to non-transformed breast epithelial MCF10A cells." (PMID 37118828, 2023). "USP37 overexpression provided a survival advantage, while its depletion heightened sensitivity to replication stress in osteosarcoma cells." (PMID 37118828, 2023).